CDX2 (caudal type homeobox 2)
Diseases named in the same sentence as CDX2 in open-access papers (continued):
Sharing a sentence is not in itself a finding about the gene and the disease.
colorectal cancer (continued). "Both the colorectal lesion and the esophageal tumors showed the CK7−/CK20 + /CDX2 + staining pattern, which suggests that the esophageal tumors originated from colorectal cancer." (PMID 37872388, 2023). "CDX-2 is expressed in colorectal cancer, plays an important role in the proliferation and differentiation of epithelial cells, and is used as a diagnostic marker." (PMID 37749564, 2023). "The study is aimed to evaluate the diagnostic and prognostic role of the immunohistochemical expression of the Caudal-type homeobox transcription factor 2 (CDX2) in colorectal cancers (CRCs) through a meta-analysis." (PMID 35328309, 2022). "Studies have shown that caudal type homeobox 2 (CDX2) acts as a tumor suppressor gene to inhibit malignant phenotypes of colorectal cancer and that the low expression of CDX2 is correlated with poor survival." (PMID 35251577, 2022). "The sensitivity of CDX2 for colorectal cancer is 99%, but CDX2 is also expressed in up to 21% of intrahepatic cholangiocarcinomas." (PMID 33852640, 2021). "The transcription factor Cdx2, and to a lesser extent Cdx1, plays essential roles in intestinal homeostasis, and acts as a context-dependent tumour suppressor in colorectal cancer." (PMID 34349205, 2021). "This is in agreement with prior observations wherein attenuation of Cdx2 in colorectal cancer cells was shown to decrease expression of markers of differentiation concomitant with an increase in proliferation." (PMID 33525395, 2021). "Colorectal cancer cells were detected by tagging CDX-2 (green), CAFs by tagging α-SMA (red), exogenous CAFs by tagging mCherry (violet), and nuclei by tagging DAPI (blue)." (PMID 34631221, 2021). "As EphrinB1 loss also leads to a villus tumor phenotype, these findings evoke a mechanism by which Cdx2 impacts colorectal cancer via Notch-dependent EphrinB1 signaling." (PMID 33525395, 2021). "CDX2 has a role in the progression of colorectal cancer and nominated as an independent prognostic factor in CRC." (PMID 33058307, 2021). "Our study aimed to investigate SATB2 expression levels and the prognostic relevance of SATB2 loss in colorectal carcinoma (CRC), especially in comparison with CDX2, the standard marker of colorectal differentiation." (PMID 34944797, 2021). "It has been reported that CDX2 knockdown promotes the proliferation of colorectal cancer cells via Wnt/β-catenin signalling." (PMID 33109187, 2020). "CDX2 inhibits colorectal cancer cell proliferation and its low expression in colorectal tumors is linked to a less favorable prognosis." (PMID 32823612, 2020). "Commonly used for differential diagnosis of colorectal cancer, caudal type homeobox 2 (CDX2) is a transcription factor critical for intestinal development that is highly expressed in normal and neoplastic intestinal epithelium." (PMID 31906589, 2020). "CDX2 expression is low in invasive colorectal cancer cells but is restored in metastases to a level corresponding to that of the primary tumour." (PMID 32408894, 2020). "A recent study showed aberrant expression of CDX2 in not only colorectal cancer but also GC and significantly higher CDX2 expression in H. pylori–positive intestinal metaplasia." (PMID 32533343, 2020). "Our results advocate the use of mIHC and DIA for research and clinical applications, here successfully shown for the colorectal cancer biomarker CDX2." (PMID 31641225, 2020). "Meanwhile, CDX2 is also involved in liver metastasis of colorectal cancer as an important member of the Wnt signaling pathway." (PMID 31216644, 2019). "The MMR status of patients with colorectal cancer should be determined before assessing CDX2 status." (PMID 30511046, 2018). "We aimed to refine the value of CDX2 as an independent prognostic and predictive biomarker in colorectal cancer (CRC) according to disease stage and chemotherapy sensitivity in preclinical models." (PMID 29900672, 2018).
colorectal cancer (continued). "In colorectal cancer, CDX2 expression is lost in approximately 20% of cases and associated with poor outcome." (PMID 30257705, 2018). "Our study suggested that the combination of CK7+/CDX2+ acquired high sensitivity and specificity in the differential diagnosis from colorectal carcinoma, which showed great application value in clinical practice." (PMID 29587865, 2018). "Another stem cell marker achaete-scute complex homolog 2 (Ascl2) is suggested to regulate the development of colorectal cancer via CDX2." (PMID 28160571, 2017). "Recent studies have shown that CDH17 is more sensitive than CK20 and CDX-2 in the diagnosis of colorectal cancer." (PMID 28969003, 2017). "Stratified by cancer types of the included studies, the CDX2 expression levels in colorectal cancer (OR: 0.80, 95%CI: [0.20,3.25], P = 0.75, I2 = 79%) and ovarian cancer (OR: 1.23, 95%CI: [0.65,2.34], P = 0.52) were irrelevant to disease relapse." (PMID 29179508, 2017). "Recent studies have revealed that CDX2 is aberrantly expressed in gastric cancer, colorectal cancer, thyroid cancer, ovarian cancer, endometrial adenocarcinoma, bladder and prostate adenocarcinoma." (PMID 27384681, 2016). "Previous studies have shown that CDX2 expression is limited not only to normal intestinal cells, but also is expressed in gastric carcinoma, colorectal cancer, thyroid cancer, ovarian cancer, urinary bladder carcinoma and prostate adenocarcinoma." (PMID 27384681, 2016). "We previously reported that the Caudal‐related homeobox transcription factor CDX2 transcriptionally regulates MDR1 expression in colorectal cancer." (PMID 27060927, 2016). "Histopathological analyses have demonstrated that the expression of CDX2 is low in invasive colorectal cancer cells, which localize at the tumor/stroma interface, but is restored in metastases, at a level corresponding to that of the primary tumor." (PMID 26005051, 2015). "CK7 negativity, CK20 positivity, and CDX-2 positivity are a frequently seen pattern in gastrointestinal cancers and particularly in colorectal cancer." (PMID 26346068, 2015). "The expression of CDX2 is correlated with the degree of colorectal cancer malignancy, and decreased expression of CDX2 indicates an increased degree of tumor malignancy and increased invasion and metastasis, which has been observed in previous studies." (PMID 26005051, 2015). "With the decreased degree of colorectal cancer differentiation, the protein expression of CDX2 appeared reduced." (PMID 26005051, 2015). "By contrast, the presence of reduced CDX2 expression levels is a predictor for poor overall survival amongst patients with colorectal cancer." (PMID 25847407, 2015). "Clinically, a reduction in CDX2 expression is correlated with poor overall survival amongst patients with colorectal cancer." (PMID 25847407, 2015). "Our previous study demonstrated that the positive rate of CDX2 was 69.4% in colorectal cancer, and 95.0% in normal colorectal tissues, suggesting that the expression of CDX2 was high in the colorectal tissues." (PMID 26005051, 2015). "Further, CDX2/AS, but not CDX2, modulates the splicing pattern of the exogenous CD44v5 and Tra2β-1 minigene transcripts in Lovo human colorectal cancer cells independently of CDX2 expression." (PMID 25101906, 2014). "To this end, we obtained a Lovo colorectal cancer cell line devoid of CDX2 expression (LovoCDX2−/−) to test the role of CDX2/AS in alternative splicing in a physiologic setting and examine the impact of CDX2 expression on CDX2/AS splicing activity." (PMID 25101906, 2014). "Mechanistically, CDX2 up regulates Wnt/β-catenin signaling, and is a key oncogenic pathway in colorectal cancer." (PMID 24489794, 2014). "The highest frequency of CDX2 staining occurred in colorectal carcinomas when compared with tumors from other sites." (PMID 25299496, 2014).
colorectal cancer (continued). "The findings of this study suggest that reduced expression of Cdx2 in primary tumors and lymph node metastases is an accurate predictor of MMR-deficiency in colorectal cancer." (PMID 24130965, 2013). "Using a tissue microarray containing more than 600 patient tissues, Baba and colleagues showed a high specificity of reduced Cdx2 expression for MSI-high colorectal cancers." (PMID 24130965, 2013). "Taken together, these data suggest a direct correlation between the expressions of Cdx2 and claudin-1 in colorectal carcinomas." (PMID 22719836, 2012). "The CDX2 is a highly sensitive marker for identifying adenocarcinomas of colonic origin, with expression observed in over 95% of colorectal cancers." (PMID 19935793, 2010). "As in colorectal cancer, expression of CDX2, VEGF-A, and EGFR was observed in the majority of cases, but HER2/neu expression and loss of PTEN expression are rare oncogenic abnormalities in this cancer." (PMID 19935793, 2010). "CDX2, another homeobox transcription factor, had been described to be methylated in squamous esophageal cancer and colorectal carcinoma, but to our knowledge, its DNA methylation in lung cancer has never been examined." (PMID 17967182, 2007). "Expression of CDX2, a caudal-related homeobox gene, was found to be decreased in colorectal carcinomas." (PMID 10027310, 1999). "Therefore, incorporating longitudinal outcome data in future cohorts will be essential to clarify the independent prognostic role of CDX2 in colorectal cancer." (PMID 41388313, 2025). "CDX2 and SATB2 have been linked to colorectal cancer (CRC) progression." (PMID 39998677, 2025). "By using CDX2—a master regulator of intestinal lineage—as a seed node, BoNE traced upstream regulatory hubs capable of reinstating epithelial identity while suppressing CSC-associated programs in colorectal cancers." (PMID 41118768, 2025). "Protein factors that could regulate transcription of SMAD4-213 via AnnoLnc2 predicted binding sites upstream of/overlapping TSS that are expressed in colorectal cancer are CDX2, CEBPB, ELF1, NCOA1, NCOR1, NCOR2 and TFAP4." (PMID 39132157, 2024). "However, we cannot draw definitive conclusions regarding the predictive value of CDX2 as a biomarker for colorectal cancer, especially in rectal or left-sided tumours." (PMID 39201360, 2024). "The most frequently mutated gene of the WNT/β-catenin pathway in colorectal cancers, APC was more often mutated in the non- CDX2-suppressed group (85% of the cases) compared with the CDX2-suppressed group (APC mutations in 40% of cases, Fisher’s exact test p < 0.0001)." (PMID 39452477, 2024). "CRLM PDOs and parent tissue expressed markers of colorectal cancer, CDX2 and CK20, consistently." (PMID 38542253, 2024). "In the TCGA cohort, the CDX2-suppressed (CDX2 log RNA Seq V2 < −2) group of colorectal cancers consisted of 75 cases (12.6% of the entire TCGA colorectal cancer cohort) and the non-CDX2-suppressed (CDX2 log RNA Seq V2 > 0) group consisted of 249 cases (41.9% of the entire TCGA cohort)." (PMID 39452477, 2024). "Lack of expression of the tumour suppressor gene caudal-type homeobox 2 (CDX2) associates with poor outcomes in early stage colorectal cancer (CRC)." (PMID 38439814, 2024). "Subsequent studies validated the prognostic impact of CDX2 in colorectal cancer." (PMID 37602699, 2023). "Thus, CDX2 is considered less specific than the CK7-negative/CK20-positive panel for colorectal carcinoma." (PMID 37174934, 2023). "In colorectal cancer, CDX2 expression was found to be down‐regulated." (PMID 33733587, 2021).
colorectal cancer (continued). "CDX2, a transcription factor, has been shown to have a decreased expression in UC, play an essential role in intestinal homeostasis, and act as a context-dependent tumor suppressor in colorectal cancer." (PMID 34992592, 2021). "In this study, we aimed to identify benefits and drawbacks with DIA and mIHC in comparison with conventional IHC analyzed according to the Allred method for colorectal cancer research and clinical use, with a particular focus on the clinically relevant markers CDX2 and SOX2." (PMID 31641225, 2020). "However, the functional role of CDX2 in the development and progression of colorectal cancer (CRC) is not well known." (PMID 30631044, 2019). "CDX2 is an independent prognostic biomarker in colorectal cancer." (PMID 29900672, 2018). "CDX2 expression may be decreased in right-sided or proximally located colon carcinomas, in poorly differentiated colorectal carcinomas as well as in colorectal carcinomas with microsatellite instability-high (MSI-H) or mismatch repair deficient (dMMR)." (PMID 29621151, 2018). "Previously, studies showed that in rat intestinal epithelium-derived line, IEC-6, caco-2 and colorectal carcinoma cells, downregulation of CDX2 by the MEK/ERK signaling pathway may decrease the protein expression levels of claudin-1, occludin and ZO-1." (PMID 30004434, 2018). "In colorectal cancer (CRC) CDX2 it has been proposed as a tumor suppressor gene." (PMID 27902469, 2017). "CDX2 expression is dramatically decreased during the late stages of malignant colorectal cancer." (PMID 28835570, 2017). "CDX-2 is intestine-specific, and immunohistochemical staining for this transcription factor has been proven able to determine whether colorectal cancer is primary or metastatic." (PMID 28969003, 2017). "CDX2 overexpression inhibits the growth and proliferation of colorectal cancer cells." (PMID 28835570, 2017). "Although CDX-2 is highly expressed in colorectal cancer tissues, it lacks specificity and may also be expressed in esophageal, gastric, and pancreatic cancer cells." (PMID 28969003, 2017). "Given the regulation of miR-196b by CDX2, a transcription factor important to intestinal epithelial cell homeostasis and disease, in this work, we wanted to explore the possible misregulation of miR-196b in colorectal cancer." (PMID 27902469, 2017). "It has been recently demonstrated that CDX2 regulates gene expression of APC and AXIN2, components of the β-catenin degradation complex, and increasing evidences indicate that CDX2 inhibits the activity of β-catenin and thereby the progression of the colorectal cancer." (PMID 26910375, 2016). "In these cases the differential diagnosis requires the use of other markers such as S-100 and other tumour specific proteins according to the presumed origin (e.g PSA for prostatic carcinoma, glypican 3 for hepatocellular carcinoma, PAX8 for renal carcinoma and CDX-2 for colorectal carcinoma)." (PMID 26888362, 2016). "However, the effect of CDX2 overexpression, as controlled by five copies of HREs and the hTERT promoter, on human colorectal cancer (CRC) cell proliferation in vitro remains to be fully elucidated." (PMID 25847407, 2015). "At present, the effects of CDX2 overexpression, under the control of five copies of HREs and the hTERT promoter, on human colorectal cancer cell proliferation in vitro remain unclear." (PMID 25847407, 2015). "This is consistent with the role of CDX2 as a tumor-suppressor gene in colorectal cancer." (PMID 25847407, 2015). "In conclusion, CDX2 exhibited notable inhibitory effects on the progression of colorectal cancer." (PMID 26005051, 2015). "In addition, CDX2 is a tumor-suppressor gene in colorectal cancer, and reduces mobility and antagonizes dissemination of colon cancer cells in vitro and in vivo." (PMID 25847407, 2015).
colorectal cancer (continued). "CDX2 may be an important tumor suppressor, which can be used as a novel index to screen and monitor colorectal cancer, and may provide a novel strategy for targeted cancer therapy." (PMID 26005051, 2015). "However, the conclusion of the present study was consistent with our previous conclusion that low gene expression levels of CDX2 in colorectal cancer accelerates the malignant growth of colorectal tumors." (PMID 26005051, 2015). "In addition, the expression of CDX2 was significantly higher in the normal colorectal tissues, compared with the colorectal cancer tissues." (PMID 26005051, 2015). "In the current study it was hypothesized that CDX2 overexpression specifically inhibits human colorectal cancer cell proliferation under hypoxic conditions." (PMID 25847407, 2015). "Western blot analysis of whole cell lysates from normal colonic mucosa and from the HT29 colorectal cancer cell line using polyclonal antisera to the unique carboxy-terminal domain of CDX2/AS revealed a 38 kD band representing the alternatively spliced protein." (PMID 25101906, 2014). "Furthermore, the tumors generated from M-SW480 cells were positive for CDX2, whose expression level is reduced in the later stages of human colorectal cancer and invasive cancer indicated by an immunohistochemical study." (PMID 25006808, 2014). "Focal Cdx2 expression was significantly more frequent in colorectal cancers with mucinous histology (p = 0.0053), higher tumor grade (p = 0.0002), more advanced pT stage (p = 0.0166), with perineural invasion (p = 0.0228), and in those receiving adjuvant therapy (p = 0.0058)." (PMID 24130965, 2013). "Expression of CDX2 in tumors other than colorectal carcinoma has been previously reported." (PMID 22268990, 2012). "Likewise, mouse chromosome 5, the only significantly gained (46%) chromosome in our colorectal cancer models, has syntenic blocks from human chromosomes 7p, 7q, and 13q, including Cdx2, which is both a lineage-specific colorectal cancer oncogene and the colorectal cancer GEMM promoter source." (PMID 41051921, 2025). "However, the prognostic significance of CDX2 expression in the context of lymph node metastasis remains a contentious topic, necessitating further investigation to elucidate its precise role in this aspect of colorectal cancer progression." (PMID 39328205, 2024). "Additionally, like in our research, Gwenzi and colleagues did not confirm that the AA and AG genotypes for Cdx2 were associated with better survival in colorectal cancer." (PMID 39519264, 2024). "Furthermore, it remains to be elucidated, how frequently the loss of SATB2 occurs in comparison to the loss of CDX2 and whether SATB2 can identify distinct prognostic groups within these colorectal cancer subsets." (PMID 34944797, 2021). "Further studies found that intestinal specific transcription factor CDX2 mediated by RNA interference (RNAi) is a trans-activator of growth-promoting gene expression in colorectal cancer, suggesting that MS4A12 may be a potential therapeutic target for colorectal cancer." (PMID 32797167, 2020). "Colorectal cancer with negative CDX2 status (CDX2−) is associated with an increased likelihood of aggressive features such as lymph node metastasis (LNM), poor differentiation, lymphovascular (LVI), perineural (PNI) and extramural vascular (EMVI) invasion, BRAF mutation and CIMP12." (PMID 30511046, 2018). "Negative CDX2 status (CDX2−) is associated with worse prognosis in colorectal cancer and may identify high‐risk stage II disease that benefits from adjuvant chemotherapy." (PMID 30511046, 2018). "Loss of expression of CDX2 in colorectal cancer has been reported as a negative prognostic marker." (PMID 28824332, 2017). "Thus, CDX2 directly regulates MDR1 expression in colorectal cancer cells." (PMID 27060927, 2016). "In addition, CDX2 expression is reduced in Dukes A-D colorectal cancer." (PMID 26005051, 2015).